GABRA4 (gamma-aminobutyric acid type A receptor subunit alpha4)
Description:
Alpha subunit of the heteropentameric ligand-gated chloride channel gated by gamma-aminobutyric acid (GABA), a major inhibitory neurotransmitter in the brain. GABA-gated chloride channels, also named GABA(A) receptors (GABAAR), consist of five subunits arranged around a central pore and contain GABA active binding site(s) located at the alpha and beta subunit interface(s). When activated by GABA, GABAARs selectively allow the flow of chloride anions across the cell membrane down their electrochemical gradient. GABAARs containing alpha-4 are predominantly extrasynaptic, contributing to tonic inhibition in dentate granule cells and thalamic relay neurons (By similarity). Extrasynaptic alpha-4-containing GABAARs control levels of excitability and network activity (By similarity). GABAAR containing alpha-4-beta-3-delta subunits can simultaneously bind GABA and histamine where histamine binds at the interface of two neighboring beta subunits, which may be involved in the regulation of sleep and wakefulness.
Tractability: Small molecule: an approved drug acts on it; a structure with a bound ligand is known; a high-quality ligand is known; it belongs to a druggable protein family. Antibody: its Gene Ontology location is reachable by antibodies, with high confidence; UniProt places it where antibodies can reach, with medium confidence; UniProt predicts a signal peptide or a membrane-spanning region. PROTAC: a small molecule that binds it is known.
Target class: Ion channel; GABA-A receptor; Ligand-gated ion channel
Safety:
Unwanted effects reported when the protein is acted on. In parentheses: how it was acted on, where the effect was seen, and who reports it.
ataxia (activation, acute dosing; central nervous system, cardiovascular; source: Lynch et al. (2017))
convulsions (inhibition, acute dosing; central nervous system, cardiovascular; source: Lynch et al. (2017))
decreased anxiety (activation, acute dosing; central nervous system, cardiovascular; source: Lynch et al. (2017))
decreased blood pressure (activation, acute dosing; central nervous system, cardiovascular; source: Lynch et al. (2017))
decreased body temperature (activation, acute dosing; central nervous system, cardiovascular; source: Lynch et al. (2017))
decreased cardiac contractility (activation, acute dosing; central nervous system, cardiovascular; source: Lynch et al. (2017))
decreased convulsions (activation, acute dosing; central nervous system, cardiovascular; source: Lynch et al. (2017))
decreased locomotor activity (activation, acute dosing; central nervous system, cardiovascular; source: Lynch et al. (2017))
decreased memory (activation, acute dosing; central nervous system, cardiovascular; source: Lynch et al. (2017))
decreased pain (activation, acute dosing; central nervous system, cardiovascular; source: Lynch et al. (2017))
decreased sleep (inhibition, acute dosing; central nervous system, cardiovascular; source: Lynch et al. (2017))
drug abuse/dependence (activation, acute dosing; central nervous system, cardiovascular; source: Lynch et al. (2017))
increased cardiac output (activation, acute dosing; central nervous system, cardiovascular; source: Lynch et al. (2017))
increased eating (activation, acute dosing; central nervous system, cardiovascular; source: Lynch et al. (2017))
increased respiratory rate (activation, acute dosing; central nervous system, cardiovascular; source: Lynch et al. (2017))
increased sleep (activation, acute dosing; central nervous system, cardiovascular; source: Lynch et al. (2017))
muscle relaxation (activation, acute dosing; central nervous system, cardiovascular; source: Lynch et al. (2017))
Gene: Protein-coding gene on chromosome 4 (46,918,900 to 46,993,581, reverse strand). Ensembl gene ENSG00000109158.
Subcellular location: Cell membrane; Postsynaptic cell membrane
Pathways (Reactome):
Neuronal System: GABA receptor activation
Gene Ontology:
Molecular function: benzodiazepine receptor activity; GABA-A receptor activity; extracellular ligand-gated monoatomic ion channel activity; monoatomic ion channel activity; signaling receptor activity; transmembrane signaling receptor activity; transmitter-gated monoatomic ion channel activity involved in regulation of postsynaptic membrane potential
Biological process: chloride transmembrane transport; gamma-aminobutyric acid signaling pathway; extrasynaptic signaling via GABA; inhibitory synapse assembly; negative regulation of synaptic transmission, GABAergic; synaptic transmission, GABAergic; chloride transport; monoatomic ion transmembrane transport; monoatomic ion transport; regulation of postsynaptic membrane potential
Cellular component: chloride channel complex; GABA-A receptor complex; dendrite membrane; plasma membrane; postsynapse; GABA-ergic synapse; membrane; postsynaptic membrane; postsynaptic specialization membrane
Genetic constraint (gnomAD): Loss-of-function variants: 8 observed, 37.49 expected, observed/expected ratio (o/e) 0.21, 90% interval 0.12 to 0.38. The upper end of that interval is the gene's LOEUF score, 0.38, which puts it in group 1 of 6, group 1 being the genes least tolerant of losing a copy. Missense variants: 450 observed, 617.72 expected, observed/expected ratio (o/e) 0.73, 90% interval 0.67 to 0.79. Synonymous variants: 257 observed, 223.61 expected, observed/expected ratio (o/e) 1.15, 90% interval 1.04 to 1.27.
Homologues: Orthologues: chimpanzee GABRA4 (100% identical), macaque GABRA4 (99% identical), pig GABRA4 (93% identical), dog GABRA4 (92% identical), mouse Gabra4 (90% identical), rat Gabra4 (89% identical), guinea pig GABRA4 (87% identical), rabbit GABRA4 (85% identical), zebrafish gabra4 (68% identical). Paralogues in human: GABRA6 (58% identical), GABRA1 (48% identical), GABRA2 (47% identical), GABRA3 (47% identical), GABRA5 (46% identical), GABRG2 (37% identical), GABRG1 (36% identical), GABRG3 (36% identical), GABRE (30% identical), GABRB1 (29% identical), GLRA2 (29% identical), GLRA3 (29% identical), and 33 more.